BCAT1 (branched chain amino acid transaminase 1)
Diseases named in the same sentence as BCAT1 in open-access papers (continued):
Sharing a sentence is not in itself a finding about the gene and the disease.
tumor (continued). "Silencing BCAT1 expression suppressed cell viability, colony formation, cycle progression, invasion, and angiogenesis of BGC823 cells, as well as the tumor growth of xenograft models, whereas overexpressing BCAT1 had the opposite results both in vitro and in vivo." (PMID 34164393, 2021). "Moreover, the Western blot results confirmed that the knockdown of BCAT1 reversed the cisplatin-induced decrease in the mTOR phosphorylation level and increase in autophagy in tumor tissues." (PMID 33568627, 2021). "In fact, bioinformatics analyses using GSE36001 dataset and qPCR assays revealed that BCAT1 was remarkably up-regulated in 157 OS specimens, indicating that BCAT1 might play a role in promoting OS tumor development." (PMID 32269179, 2020). "Since the silencing of BCAT1 alone couldn’t suppress the tumor growth, the co-amplified genes might play a role in supporting tumorigenesis which needs further validation." (PMID 33488950, 2020). "The variables that related to degree of methylation in tissue was cancer compared to non-cancer tissue (either marker), age (lower methylation in younger people in cancer tissue, BCAT1 only) and tumour location (higher methylation in proximal locations, BCAT1 only)." (PMID 29796114, 2018). "BCATc, also known as BCAT1, represents the major BCAT isoenzyme implicated in tumour progression." (PMID 30318512, 2018). "In HCC, BCAT1 expression was higher in tumor tissue compared to non-tumor tissue, and was associated with resistance to chemotherapy and poor prognosis." (PMID 30265706, 2018). "In several tumor types, the epigenetic dysregulation of BCAT1 expression has been elucidated." (PMID 29211698, 2018). "Therefore, GBMs with a low expression level of BCAT1 tend to have a slow growing nature, resulting in a relatively large tumor volume based on FLAIR images." (PMID 29255149, 2017). "Knockdown of BCAT1 dramatically reduced the rates of cell proliferation, migration and invasion, and silencing of BCAT1 was reported to suppress ovarian tumorigenesis and induce the expression of several tumor suppressors." (PMID 28122348, 2017). "Therefore, how BCAT1 reprograms BCAA metabolism to support tumor progression is complex and could be cell context- and stress context-dependent." (PMID 39143065, 2024). "Similarly, the fluorescent orthotopic tumour xenograft model showed that the sizes of localized tumour xenografts and metastatic lesions were notably increased in mice inoculated with BCAT1-overexpressing PC3 cells compared with mice inoculated with vector control cells at 3 weeks." (PMID 38369471, 2024). "Interestingly, all the genes of the pathway were significantly downregulated in the tumor samples, except for the Branched-Chain Amino Acid Transaminase 1 (BCAT1) and the lysosomal amino acids oxidase Interleukin 4 Induced 1 (IL4I1), which were strongly upregulated." (PMID 36539415, 2022). "In addition, BCAT1 also plays a role in resistance to tumor therapy." (PMID 36119495, 2022). "Therefore, the upregulation of both cystathionine and BCAT1 promotes the growth of a tumor." (PMID 35574395, 2022). "This suggests that BCAT1 may be a biomarker for tumor subtype classification." (PMID 36119495, 2022). "Besides, patients with high BCAT1 expression are also more likely to develop tumor recurrence." (PMID 33493139, 2021). "Moreover, the low levels of all three BCAAs may be due to a decrease in BCAA transaminase 1 (BCAT1) expression/activity, consistently, again, with lower mTORC1 activation in 59-2-HI tumours." (PMID 32867141, 2020). "If detection of methylated BCAT1/IKZF1 ctDNA is to be useful in patient management, it is important to better understand the principles underlying the presence of these epigenetic markers in blood and how this relates to tissue expression and to tumour debulking." (PMID 29796114, 2018).
tumor (continued). "Further RRM2, GMPS, BCAT1, PYCR2, and NEU1 are identified in tumor tissue as actionable candidates for prevention." (PMID 40290517, 2025). "Molecularly, this reprogramming involves coordinated changes in transporters (like LAT1), enzymes (BCAT1/2, BCKDH, BCKDK), and signaling pathways (mTORC1 and beyond) that together promote tumor proliferation, survival under stress, and metastasis." (PMID 41502503, 2025). "Treatment with L-β-hydroxyisoleucine (LβhL), a leucine analog and competitive inhibitor of BCAT1, can reduce IL-17 production in TCR-activated CD4+ T cells, thus weakening the immune response in the tumor microenvironment." (PMID 40438606, 2025). "Inhibiting BCAT1 can impair BCAA metabolism, suppress tumor growth, and reduce cancer cell proliferation." (PMID 40469185, 2025). "The methylation status of BCAT1 has also been used as a biomarker for non-invasive CRC diagnosis, highlighting its potential in early tumor detection." (PMID 40313460, 2025). "Consistent with this concept, recent work has demonstrated metabolism-directed strategies to overcome EGFR-TKI resistance, including inhibition of BCAT1/BCAA metabolism and disruption of kynurenine–AHR signaling in the tumor microenvironment." (PMID 41142757, 2025). "The results showed that silencing BCAT1 decreased cell viability, colony formation, cycle progression, invasion, and angiogenesis in BGC823 cells and reduced tumor growth in xenograft models." (PMID 39409942, 2024). "BCAT1 likely modulates components of the WNT signaling pathway, further promoting tumor cell invasion and migration." (PMID 39324007, 2024). "The key enzymes involved in BCAA catabolism, mainly BCAT1/2 and BCKD, are elevated in tumors of the liver and breast." (PMID 38631892, 2024). "The enzyme branched-chain amino acid transaminase 1 (BCAT1) catalyses the breakdown of BCAAs and is frequently upregulated in tumours." (PMID 39796683, 2024). "Future studies should focus on identifying the direct and indirect targets of BCAT1 within these pathways and elucidating their roles in EMT and tumor progression." (PMID 39324007, 2024). "By quantifying the expression of BCAT1/2 in each specimen, we confirmed that the expression of BCAT1 and BCAT2 was significantly increased in tumours." (PMID 37076565, 2023). "The expression of genes involved in the degradation of BCAA decreased but BCAT1 and BCAT2 were upregulated in the tumour tissues." (PMID 37076565, 2023). "The core TAM2-driven genes, including BCAT1, BST2, and MERTK, are involved in regulating tumor progression and TAM2 polarization, which are potential targets for PC therapy." (PMID 37628967, 2023). "This observational study showed a correlation between the levels of methylated BCAT1/IKZF1 ctDNA and tumor burden." (PMID 35000264, 2022). "The mechanism by which BCAT1 and c-Myc genes co-regulate cancer cell proliferation and invasion have been found in many cancers, such as HNSC, NPC, LC and other tumor types." (PMID 36119495, 2022). "Following extraction from blood samples, the cfDNA was analyzed for methylation in the BCAT1 and IKZF1 genes, resulting in a strong correlation between tumor aggressiveness and positivity rates delivered through testing." (PMID 36359889, 2022). "In the current study, we have extended on our previous findings and have shown a close relationship between the amount of circulating methylated BCAT1/IKZF1 DNA and tumor burden at diagnosis." (PMID 35000264, 2022). "More importantly, LY294002, an inhibitor of the PI3K/AKT/mTOR pathway, markedly reversed BCAT1-mediated tumorigenicity, including the phosphorylation of AKT; increased cell viability, proliferation, invasion, and angiogenesis; and tumor growth." (PMID 34164393, 2021). "Immunohistochemistry analysis also showed that the knockdown of BCAT1 increased the cisplatin sensitivity, resulting in higher expression levels of cleaved caspase-3 and TUNEL, and a lower expression level of Ki-67 in tumor tissues." (PMID 33568627, 2021).
tumor (continued). "However, whether BCAT1 plays a role in tumor metastasis is less well known." (PMID 34646394, 2021). "Then, mutual relationship analysis of BCAT1 related immune cells was further conducted to identify their clusters according to IDH status and tumor grades." (PMID 33493139, 2021). "BCAT1-mediated BACC catabolism is a conserved regulator of diverse physiological and pathological processes, including tumor development." (PMID 34164393, 2021). "Most of these genes are enzymes in the metabolism of tumor cells, such as HS3ST3B1, GLUD1, BCAT1, and ACAA2." (PMID 32280672, 2020). "Unexpectedly, the percentage of BCAT1 was positively correlated with the EMT process, suggesting a potential marker for CTCs to evaluate tumor metastasis and recurrence." (PMID 32610709, 2020). "The role of BCAT1 and BCKDK in BCAAs metabolism and the significant status of BCAT1 in tumor progression, raises several questions: Is there any relationship between BCKDK and BCAT1 in CRC development?" (PMID 32238881, 2020). "ctDNA methylated in BCAT1 or IKZF1 was detected in 116 (62.0%) cases at diagnosis and was significantly more likely to be detected with later stage (P < 0.001) and distal tumour location (P = 0.004)." (PMID 29796114, 2018). "From the tumor extents based on FLAIR images, the BCAT1 expression level was significantly correlated with the mean nCBV, 95% nCBV, and mean ADC (r = 0.2879, 0.2567 and −0.2562, respectively; in all, P < 0.05)." (PMID 29255149, 2017). "The correlation analysis between the BCAT1 expression level or MGMT promoter methylation status and quantitative values from tumor volumetrics and nCBV and ADC histograms were performed." (PMID 29255149, 2017). "To investigate the role of BCAT1 in tumor cells, we used the IDH1 WT-expressing human U87 MG GBM cell line and stably knocked down BCAT1 using shRNA." (PMID 27626306, 2016). "In vivo MRI showed that the increase in both tumor volume and nCBV after bevacizumab treatment in IDH1 WT tumors was significantly higher compared with BCAT1 sh#1tumors." (PMID 27626306, 2016). "We evaluated off-target effect of shRNA by using a second shRNA (BCAT1 sh#3), which reveals which revealed similar change to IDH WT tumors in terms of both tumor volume and nCBV." (PMID 27626306, 2016). "The biological functions of BCAT1 and IKZF1 are not well understood, but both genes are involved in tumour growth and invasiveness." (PMID 26445409, 2015). "We optimized the BCAT1 and IKZF1 methylation qPCR assays for detection of methylation ratios as low as 0.1%, as such low levels of tumour-derived DNA have been reported in plasma specimens from patients with early stage CRC." (PMID 25928810, 2015). "In tumor tissue, these pathways were significantly deregulated regarding gene and protein expression in two independent datasets, including actionable targets RRM2, GMPS, BCAT1, PYCR2, and NEU1." (PMID 40290517, 2025). "The importance of BCAT1 as a therapeutic target is highlighted by the discovery of a small-molecule BCAT1 inhibitor, eupalinolide B (EB), which induced apoptosis in TNBC cells and showed anti-tumor effects in preclinical models." (PMID 41502503, 2025). "In addition, branched‐chain amino acid transaminase 1 (BCAT1) is upregulated in GB resulting in a high rate of BCAA conversion to branched‐chain α‐ketoacids, which promote immunosuppression and tumor growth." (PMID 39992790, 2025). "Similarly, in glioblastoma, BCAT1 upregulation (via the histone methyltransferase DOT1L) increased BCAA catabolism and supplied glutamate for antioxidant defenses, promoting tumor cell proliferation under stress." (PMID 41502503, 2025). "Additionally, studies suggest that co-targeting stromal BCAT1 and the cancerous BCKDH complex impairs tumor cell proliferation and survival." (PMID 40438606, 2025). "The loss of enzymes responsible for BCAAs utilization, Bcat1 and Bcat2, impairs NSCLC tumor formation, although these enzymes are not essential for PDAC tumor formation." (PMID 40438606, 2025).
tumor (continued). "Additionally, branched-chain amino acid transaminase 1 (BCAT1) and solute carrier family 2 member 1 (SLC2A1)—genes known to promote cancer cell invasion and tumor immune infiltration, respectively—were also up-regulated in the Liver ECM group." (PMID 40852642, 2025). "For instance, lncRNA-BCAT1 is significantly decreased in HCT116 and SW480 cells, implying its tumor-suppressing role in CRC, while overexpression of BCAT1 may lead to lower proliferation." (PMID 39026221, 2024). "For example, BCAAs metabolic reprogramming was exhibited in tumor tissues of both S-III and DEN and CCl4-induced HCC mouse models, but upregulation of BCAT1 and BCAT2 was detected in tumor tissues of S-III, whereas only upregulation of BCAT2 was detected in DEN and CCl4-induced HCC mouse model." (PMID 38580754, 2024). "Increased expression of branched-chain amino acid (BCAA) transaminase 1 (BCAT1) often correlates with tumor aggressiveness and drug resistance in cancer." (PMID 39769333, 2024). "Identification of such patients by means of assaying for circulating DNA methylated in BCAT1/IKZF1 does not require genomic analysis of the tumor tissue." (PMID 35822405, 2023). "Here, we demonstrated that detection of circulating methylated BCAT1/IKZF1 DNA is indicative of the presence of tumor even if it is not radiographic apparent." (PMID 35822405, 2023). "The expression of BCAT1 and BCAT2 was upregulated in tumours in the three cohorts." (PMID 37076565, 2023). "We found that ~40 enzymes involved in BCAA catabolism were suppressed in tumours, with the exception of BCAT1 and BCAT2 that were upregulated in the transcriptome but not detected in the proteome." (PMID 37076565, 2023). "Moreover, BCAT1 acted as a prognostic biomarker for HCC and promoted tumor progression via the AKT signaling pathway and EMT." (PMID 37725627, 2023). "Notably, the expression of BCAT1 and BCAT2 was ubiquitously upregulated in tumour samples relative to that in the respective normal tissues in our multi-sampling cohort." (PMID 37076565, 2023). "The genes encoding proteins involved in production of the branched-chain amino acids leucine, isoleucine and valine (BCAT2, BCAT1) were also increased in tumor vs. non-transformed tissue." (PMID 36831650, 2023). "In this study, we assessed BCAT1 and IKZF1 methylation levels to quantify circulating tumor DNA (ctDNA) and investigated whether this method can be used to assess tumor burden and efficacy of therapy." (PMID 35000264, 2022). "The IHC results indicated that the expression levels of BCAT1 protein were significantly up‐regulated in SCLC tumour tissues compared to normal lung tissues, although its expression was variable among tumour tissues from different SCLC patients." (PMID 35318805, 2022). "Of the 81 positive cases without neoplasia, 62 (76.5%) were positive by a single PCR replicate only and predominantly due to detection of methylated BCAT1 (53.2%)." (PMID 33478584, 2021). "The odds ratio for presence of CRC compared to those without neoplasia was 25.9 (95% CI 17.3–38.4) for the multi-target assay (any gene positive) compared to 39.8 (95% CI 25.7–61.5) if using the ‘BCAT1 replicate rule’." (PMID 33478584, 2021). "Single replicate positivity was significantly higher than that in CRC (26/136, 19.1%, p < 0.0001), and single BCAT1 replicate positivity was more likely in cases without neoplasia than in CRC (OR 17.7, 95% CI 6.6–43.3, p < 0.0001)." (PMID 33478584, 2021). "More than half of the single PCR replicate positive cases without neoplasia were due to detection of methylation in BCAT1 (33/62, 53.2%)." (PMID 33478584, 2021). "We observed a lower level of BCAT1 expression in the high-TIL group, which may have reflected an immune reaction and suppression of tumour progression, leading to a favourable prognosis in patients with TNBC." (PMID 32571264, 2020). "Injection of BCAT1 silenced cells did not affect tumor size and volume of the ascites compared to the control." (PMID 33488950, 2020).